ANKRD36B (ankyrin repeat domain 36B)
Synonyms: FLJ21281; KIAA1641
Tractability: PROTAC: ubiquitination databases record sites on it.
Gene: Protein-coding gene on chromosome 2 (97,492,663 to 97,589,877, reverse strand). Ensembl gene ENSG00000196912.
Subcellular location (Human Protein Atlas): Cytosol; Nucleoplasm
Gene Ontology:
Molecular function: protein binding
Genetic constraint (gnomAD): Loss-of-function variants: 30 observed, 71.56 expected, observed/expected ratio (o/e) 0.42, 90% interval 0.31 to 0.57. The upper end of that interval is the gene's LOEUF score, 0.57, which puts it in group 2 of 6, group 1 being the genes least tolerant of losing a copy. Missense variants: 460 observed, 551.56 expected, observed/expected ratio (o/e) 0.83, 90% interval 0.77 to 0.9. Synonymous variants: 155 observed, 184.3 expected, observed/expected ratio (o/e) 0.84, 90% interval 0.74 to 0.96.
Homologues: Orthologues: dog ANKRD31 (11% identical), tropical clawed frog ankrd31 (7% identical), Drosophila melanogaster pain (6% identical). Paralogues in human: ANKRD36C (92% identical), ANKRD36 (90% identical), ANKRD31 (11% identical).
Diseases named in the same sentence as ANKRD36B in open-access papers:
ANKRD36B is named in the same sentence as 2 diseases in open-access papers, as found by Europe PMC text mining. Sharing a sentence is not in itself a finding about the gene and the disease.
ANKRD36B shares sentences with these, for which no sentence is quoted: ovarian carcinoma (1 paper); tumor (1).